BRCA1 (BRCA1 DNA repair associated)
Diseases named in the same sentence as BRCA1 in open-access papers (continued):
Sharing a sentence is not in itself a finding about the gene and the disease.
breast cancer (continued). "While BRCA1/2 PVs have an extensive influence on tumourigenesis by affecting the tumour microenvironment, the differences in epigenetics of hereditary and sporadic breast cancers also predispose hereditary BRCA1 PV carriers and, to a lesser extent, BRCA2 ones, to the development of cancer." (PMID 39682099, 2024). "Similarly, the presence of BRCA1/BRCA2 mutations in breast cancer patients may influence the risk of complications after radiation, like brachial plexopathy, though the data is conflicting." (PMID 40191738, 2024). "In addition to the best-known pair of genes that can predispose a patient to the development of breast cancer, namely the BRCA1 and BRCA2 genes, there are other genes with variable penetrance that can in some way increase the predisposition to this type of neoplasm." (PMID 36835955, 2023). "Thus, the best AUC which could be expected for ovarian cancer predictive tests based on family history and supplemented with information on BRCA1/BRCA2 mutation status is probably similar to that for breast cancer, or about AUC = 0.60–0.65." (PMID 36981032, 2023). "The AhR enhances the release of amphiregulin (AREG) and specific chemokines including granulocyte-colony stimulating factor (G-CSF), CXCL1/2/5, and CCL2/5 in the TME in human breast cancer tissue bearing BRCA1 mutation, which may facilitate the activation of protumorigenic and angiogenic TAMs." (PMID 37241719, 2023). "Therefore, some studies suggested that Chinese women should receive breast cancer prevention knowledge education, especially those who are at high risk of carrying BRCA1 or BRCA2 germline mutations, as studies have shown that BRCA1/2 mutations can lead to hereditary breast cancer." (PMID 36613148, 2023). "It has therefore been suggested that the Newfoundland and Labrador young female population may carry a higher prevalence of genetic mutations, carrying an increased risk for breast cancer such as BRCA1/2, predisposing them to these more aggressive tumor biologies, such as triple-negative disease." (PMID 37999115, 2023). "Triple-negative breast cancer (TNBC), a biological and clinically heterogeneous disease, accounts for 15 to 20% of all breast cancers (BC) and is more common in premenopausal women or those with breast cancer gene 1 (BRCA1) gene mutation." (PMID 37686205, 2023). "Up to ~25% of hereditary BC can be explained by the existence of highly penetrant risk variants in the tumor suppressor genes BReast CAncer gene 1 (BRCA1) and BReast CAncer gene 2 (BRCA2)." (PMID 37627152, 2023). "Additionally, patients with BRCA1 mutations are more likely to develop breast cancer at a younger age, when the disease may be more aggressive and therefore more likely to be diagnosed at an advanced stage." (PMID 38098088, 2023). "The exact cause of BC is unknown, but several factors can increase the risk of developing it, including age, family history of breast cancer, inherited gene mutations (such as BRCA1 and BRCA2), obesity, hormonal imbalances, and exposure to certain environmental factors." (PMID 37509426, 2023). "Furthermore, patients with HER2-negative early breast cancer and germline BRCA1 or BRCA2 variants could also benefit from adjuvant Olaparib treatment." (PMID 38274092, 2023). "In addition, whether breast cancer cells have breast cancer susceptibility gene 1 (BRCA1) and BRCA2 mutations affects their responses to treatment differently." (PMID 37762330, 2023). "Similarly, the fraction of breast cancers attributable to mutations in BRCA1 or BRCA2 is about 10%." (PMID 36981032, 2023).
breast cancer (continued). "Thus, reduced expression of H19 or ILF2 might serve as a biomarker for determining breast cancer patients with BRCA1 deficiency or low BRCA1 for consideration for use of PARP inhibitors for adjuvant therapy." (PMID 37298108, 2023). "Similarly, expression of RING domain-deficient BRCA1 (Rdd-BRCA1) has been observed in mammary tumours of mice carrying the BRCA185stop founder mutation which does not require interaction with BARD1 for protein stability, enabling normal HR function in the presence of PARP inhibition." (PMID 37430137, 2023). "Because of this range of variation, other genetic and non-genetic factors could play a role in radiosensitive patients too, including single-nucleotide polymorphisms or mutations in other relevant genes as have been studied in non-BRCA1/2-mutated breast cancer patients." (PMID 37623237, 2023). "Based on the limited evidence available, there are indications that physical activity during the formative years of adolescence and young adulthood may decrease or postpone the occurrence of breast cancer in individuals carrying BRCA1 and BRCA2 P/LP germline variants." (PMID 37628558, 2023). "Pathogenic variants in the BRCA1/2 genes are associated with a 55%–72% lifetime risk for breast cancer (BC), 26%–83% for contralateral BC, and 17–59% for ovarian cancer." (PMID 35941731, 2023). "Moreover, loss of 53BP1 has also been observed in patient-derived tumor xenograft (PDX) models with acquired resistance to PARPis, and mutations in TP53BP1 have been reported in tumor biopsies from patients with metastatic BRCA1-associated breast cancer receiving platinum chemotherapy or PARPis." (PMID 37209095, 2023). "However, the efficacy of pharmacotherapies for patients with advanced breast cancer carrying BRCA1/2 pathogenic variants remains unclear." (PMID 36865806, 2023). "In breast cancer cells, mutations in BRCA1 and BRCA2 differentially modulate the tumor-immune microenvironment, which may be partially due to distinct mutational and copy number profiles, resulting in differential responses to checkpoint blockade immunotherapy." (PMID 37174127, 2023). "However, BRCA1 was associated with an increased risk of ER-negative disease and was identified as a high-risk gene among case patients who had a first-degree relative with breast cancer." (PMID 37790698, 2023). "Efforts are underway to better characterize the patterns associated with PVs in non-BRCA1/2 breast cancer-predisposition genes in order to describe gene-specific risk factors for carrying a PV and to inform testing guidelines across all women with breast cancer or a familial cancer risk." (PMID 37084156, 2023). "While a risk-reducing bilateral mastectomy may reduce breast cancer incidence for carriers of both pathogenic variants, as well as mortality for BRCA1 pathogenic variant carriers, worsening of body image and sexual satisfaction have been reported, even with immediate reconstruction." (PMID 37185387, 2023). "In the Breast Cancer Linkage Consortium (BCLC), carriers of BRCA1 mutations showed less DCIS around the invasive lesion compared with controls (sporadic BC cases) (41 vs 56%)." (PMID 36349178, 2022). "Given the fact that low levels of BRCA1 have been correlated with the initiation and progression of sporadic breast cancer, this molecular mechanism may explain the finding that prolonged stress signaling increases breast cancer risk." (PMID 35432218, 2022). "Among them, breast cancer susceptibility gene 1 (BRCA1) is one of the most common tumor suppressor genes, which encodes a 220 kD nuclear protein and is detected in at least 5% of unselected patients with BC." (PMID 35300412, 2022). "Moreover, another in-depth TCGA analysis also pointed to the coexistence of anti-tumoral immune transcripts downregulation, such as IFN-γ related genes, with the upregulation of immunosuppressive markers related to myeloid tolerogenic cells activity in BRCA1 mutated breast cancers." (PMID 35211121, 2022).
breast cancer (continued). "Thus, it reports the relevant findings of scientific literature on the outcome of the conservative surgical approach to hereditary breast cancer linked to pathogenic mutations in high penetrance genes, focusing on BRCA1 and 2 genes, potentially helpful in daily clinical practice." (PMID 35805017, 2022). "Thus, RHAMM has been linked with increased breast cancer susceptibility in BRCA1 mutation carriers." (PMID 36033439, 2022). "Although the exact mechanism for the increased levels of PD-1 and PD-L1 in BRCA1-deficient breast cancers remains elusive, we believe pSTAT3 might play an important role in this as a previous study has indicated that STAT3 activation could be responsible for the increased expression of PD-L146." (PMID 35304461, 2022). "Provided the association between higher CAV1 and BRCA1 deficiency or basal phenotype, that are both risk factors for contralateral breast cancer, cytoplasmic CAV1 may be a proxy marker for these factors, representing a tumor phenotype that tends to occur in the contralateral breast." (PMID 35660849, 2022). "Therefore, defect in DNA damage repair and impairment of mammary stem cell differentiation could be two plausible mechanisms for those breast cancers with loss of or insufficient BRCA1." (PMID 35280675, 2022). "However, BRCA1/2-associated breast cancer is accompanied by a defect of homologous recombination repair function, which may be more sensitive to DNA-damaging drugs, such as platinum drugs or poly-ADP ribose polymerase inhibitors." (PMID 35402620, 2022). "Inherited pathogenic variants (PVs) in the BRCA1/2 genes are the most common cause of hereditary breast cancer (BC)." (PMID 35761208, 2022). "A breast cancer gene 1 (BRCA1) or BRCA2 gene mutation is thought to be responsible for 2% to 3% of all cases of BC." (PMID 35889394, 2022). "However, RRBM-RRBSO or just RRBSO was the most effective risk-reducing strategy in patients with TN breast cancer aged over 40 years with the BRCA1 pathogenic variant in exons 12-24 in stage II and in patients aged over 35 years with the BRCA2 pathogenic variant in exons 12-24 in stage II." (PMID 36580360, 2022). "Furthermore, the BRCA1/BARD1 heterodimer interaction was disrupted by BARD1 or BRACA1 mutations associated with the presence of breast cancer, such as mutations of the RING finger domain, missense mutations, and alterations of ANK sequences that are involved in the regulation of transcription." (PMID 35650591, 2022). "However, such treatment has been linked to increased incidences of mammary tumors, especially within female jaguars, which can develop mammary tumors in a manner similar to humans carrying a BRCA1 genetic mutation that allows uncontrolled mammary cell proliferation." (PMID 36551658, 2022). "However, BRCA1/2 mutation occurs frequently in breast cancer." (PMID 35409110, 2022). "In well-powered GWAS, even relatively rare large-effect coding alleles (mutations in BRCA1 that cause breast cancer, for instance) may be detectable as an association to common variants, which could make the effect of a coding variant appear to be regulatory instead." (PMID 36515579, 2022). "Most studies have shown that hnRNPA2/B1 was increased in BC, negatively correlated with cancer suppressor breast cancer susceptibility gene 1 (BRCA1), and was a marker of poor prognosis in patients with BC." (PMID 35879279, 2022). "In addition, F06 exhibited a synergy with PARPi olaparib in BRCA1-deficient breast cancer cells." (PMID 35463312, 2022). "Indeed, breast cancer cells with BRCA1 deficiency caused downregulation of 14-3-3 sigma and could not hinder cell-cycle progression towards the G2/M phase." (PMID 35890172, 2022).
breast cancer (continued). "Our results support the hypothesis that breast cancer risk for women carrying large deletions in BRCA1 is greater than those pathogenic single nucleotide variants or Indels, which may have implications for clinical risk assessment and management of CNV carriers." (PMID 36203093, 2022). "The ORs for BRCA1 in contrast were as high as expected for overall breast cancer risk; however this may reflect the rather low carrier frequency in the control population of only two of 1567 individuals, as well as the strong family histories of breast and/or ovarian cancer." (PMID 33763779, 2022). "Our findings support the use of mutational profiling of Chinese breast cancer patients with these characteristics to assess the presence of germline mutations in BRCA1/2 and other DDR pathway genes in order to identify patients who may benefit from treatment with PARP inhibitors." (PMID 35494038, 2022). "Given that the BRCA1 gene was identified over 20 years ago, that preventive mastectomy remains the gold standard, and that mutation carriers have strong preferences for chemoprevention, it is timely that an effective breast cancer risk reduction option be identified." (PMID 35418083, 2022). "In addition to that, breast cancer patients are screened for BRCA1/2 mutations, which may determine the severity of the disease and determine the therapeutic options and response time of the patient." (PMID 35163783, 2022). "However, several of our premenopausal breast cancer patients carried germline variants of unknown/uncertain significance (VUSs) in eight different breast cancer susceptibility genes, namely BRCA1, BRCA2, CHEK2, RAD51C, RAD51D, ATM, BRIP1, and PMS2." (PMID 36011273, 2022). "Importantly, in a prospective analysis by our group, we previously showed that combined HRT use following an oophorectomy has been reported to increase the incidence of breast cancer compared to estrogen-alone HRT among 872 BRCA1 mutation carriers who underwent bilateral oophorectomy." (PMID 35418083, 2022). "However, even in the responsive patients, olaparib only moderately extended life, from 4.2 months to 7 months on average, in comparison with the standard therapy group, which highlights the need for effective therapeutic treatment strategies for BRCA1 mutation–associated breast cancer." (PMID 35025764, 2022). "Rare, highly penetrant mutations in genes such as BRCA1/2, identified by linkage/positional cloning in breast cancer families more than 20 years ago, remain the single largest known genetic risk factor for breast cancer, accounting for ~30% of excess familial risk." (PMID 34359817, 2021). "Finally, we have demonstrated that loss of p16 or p18 rescues the premature senescence of MECs caused by Brca1 deficiency and that loss of Brca1 in p16- or p18-deficient mice leads to the development of mammary tumors resembling BLBC accompanied by features of EMT." (PMID 33478572, 2021). "Moreover, miR-155, induced by FOXP3 through transcriptional repression of BRCA1, is associated with tumor initiation in human breast cancer, suggesting that plasma miR-155 may serve as a non-invasive biomarker for detection of early-stage breast cancer." (PMID 34768829, 2021). "However, other attributes of the ABCFS participants and the nature of the breast cancer risks associated with pathogenic variants in genes other than BRCA1 and BRCA2 may partially provide an explanation." (PMID 34887416, 2021). "Furthermore, from candidate markers for BRCA1 mutant tumors, we discovered and validated one oncogene Mrc2, whose loss could reduce mammary tumor growth in vitro and in vivo." (PMID 34815798, 2021). "Indeed, more than 44.44% of carriers harbor BRCA1-c.211dupA or BRCA2-1310_1313deAAGA mutations which highlights the importance of screening these mutations in the treatment workflow of cases with early onset or strong family history of breast cancer." (PMID 34490083, 2021).
breast cancer (continued). "Furthermore, some missense variants may exhibit partially reduced activity sufficient to confer a moderately increased risk of breast cancer, as shown for R1699N substitution in BRCA1 or Y3035S in BRCA2." (PMID 34359619, 2021). "Therefore, we hypothesize that breast cancers with either high levels of LMWE or harboring BRCA1/2 mutations are more sensitive to PARPi than those breast cancers with low levels of cyclin E and wildtype BRCA1/2." (PMID 33916118, 2021). "In addition to the established predictive importance of BRCA1/2 mutation status in evaluating breast cancer risk, the identification of carriers of BRCA1/2 mutations has significant implications in guiding surgical, radiotherapeutic, and drug treatment options." (PMID 34206661, 2021). "Additionally, If the decreased ovarian reserve in BRCAm1 will be confirmed in future trials, the possible increased risk of gonadotoxicity in breast cancer patients carrying the BRCA1 pathogenic variant should be another issue to consider when counseling these patients." (PMID 34627117, 2021). "However, risk reduction for breast cancer after RRBSO in BRCA1/2 mutation carriers may have been overestimated because of selection bias in the existing observational studies." (PMID 33885953, 2021). "Besides their impact on the susceptibility to breast cancer, BRCA1/2 mutations may be linked to distinctive clinical course and biological features." (PMID 34206661, 2021). "However, it has been previously reported that the frequency of PIK3CA mutations may be different in breast cancer patients based on the presence of germline mutations in BRCA1/BRCA2 (in both women and men)." (PMID 34287479, 2021). "Interestingly, in breast cancer, loss of BRCA1 protein is associated with EMT." (PMID 34356119, 2021). "Besides, we identified some marker genes for BRCA1 deficient mammary tumors, which may serve as candidate targets for diagnosis, prognosis and/or treatment of BRCA1 associated breast cancers." (PMID 34815798, 2021). "Interestingly, MCF-7 breast cancer cells have a BRCA1 gene loss that may have contributed to the detected levels of immune gene activation and micronuclei formation." (PMID 34139015, 2021). "In BC settings, germline mutations of BRCA1/2 genes are frequent in patients with the triple negative breast cancer (TNBC) molecular subtype." (PMID 34771640, 2021). "Thus, the BRCA2-associated risk could be higher for pancreatic than for breast cancer, as indicated by our analysis of pooled patients against gnomAD data (BRCA1: OR = 6.0 vs. BRCA2: OR = 11.7)." (PMID 34503238, 2021). "The RECAP test allowed identification of HRD tumor specimens beyond those carrying BRCA1/2 pathogenic variants in breast cancer (BC), endometrial cancer (EC) and ovarian cancer (OC)." (PMID 34203855, 2021). "In addition, women who develop breast cancer at an older age and report a strong family history of breast/ovarian cancer mainly in close relatives—first, second, or third degree—may also be BRCA1/BRCA2 mutation carriers." (PMID 34287479, 2021). "However, in France, women presenting with these mutations are not included in the organized nationwide screening and, as explained in PROCAS12, mutations in breast cancer genes such as BRCA1 and BRCA2 are too infrequent to affect risk prediction appreciably in the models for the general population." (PMID 34580360, 2021). "Similarly, breast cancer cell lines are very heterogeneous and defined in part by differences in their mutational status in the breast cancer tumor suppression gene (BRCA1), estrogen receptor (ER), progesterone receptor (PR), and human epithelial receptor 2 (HER2)." (PMID 34371784, 2021).